UBA2 (ubiquitin like modifier activating enzyme 2)
Diseases named in the same sentence as UBA2 in open-access papers (continued):
Sharing a sentence is not in itself a finding about the gene and the disease.
tumor (19 papers, 2020 to 2025). "To further verify the role and underlying mechanism of UBA2 in ccRCC, we constructed a nude mouse model of subcutaneous tumor formation." (PMID 34753901, 2021). "The pVEC-ASO3 demonstrates an equal cytotoxic effect at the highest concentration in both tested tumor cell lines with the UBA2 gene." (PMID 38391508, 2024). "It highlights UBA2 as a potential therapeutic target for intervention strategies aimed at inhibiting tumor growth and metastasis in LUAD." (PMID 38407971, 2024). "Both mRNA and protein expression levels of UBA2 were found to be higher in ccRCC than in normal renal tissues and significantly related to the tumor size, Fuhrman grade, and tumor stage." (PMID 34753901, 2021). "Silencing UBA2 can reduce tumor cell migration and invasion ability and increase the sensitivity to etoposide and cisplatin." (PMID 33898460, 2021). "The analysis from GEPIA database showed that the UBA2 mRNA expression levels were higher in tumor tissues than in normal tissues." (PMID 34753901, 2021). "Recent studies indicate that SAE1/UBA2, a heterodimer that catalyzes the first step of the SUMOylation cascade, is involved in regulating tumor growth and metastasis." (PMID 32938830, 2020). "SUMO1, Uba2, and Ubc9 upregulation in PCs could lead to enhanced SUMOylation of the TF ETS variant 1 (ETV1), and blocking ETV1 tumor-promoting activity by SUMOylation could suppress the growth of PC." (PMID 35465332, 2022). "Moreover, UBA2 participates in the processes of tumor progression, invasion, and metastasis through the Wnt-dependent pathway, consequently promoting epithelial–mesenchymal transition." (PMID 35992817, 2022). "Moreover, the expression levels of UBA2 were significantly related to the tumor size, Fuhrman grade, and tumor stage." (PMID 34753901, 2021). "Thus, UBA2 knockdown inhibited the tumor growth and promoted apoptosis, while UBA2 overexpression promoted the tumor growth and suppressed apoptosis in vivo." (PMID 34753901, 2021). "However, the role of UBA2 in LSCC tumor progression is unclear." (PMID 37056932, 2023). "Remarkably, the combined knockdown of UBA2, RALY, and FOXD1 largely suppressed xenograft tumor growth and VM and prolonged nude mice survival." (PMID 37906341, 2023). "Remarkably, the combined knockdown of UBA2, RALY, and FOXD1 resulted in the smallest tumor volumes and the longest survivals of nude mice in vivo." (PMID 37906341, 2023). "Compared with the control groups, the sh-UBA2, sh-RALY, and sh-FOXD1 groups showed smaller tumor volumes." (PMID 37906341, 2023). "Further subgroup analyses indicated that SAE1 and UBE2I had differential expressions with different stages, while SENP1, USPL1, SENP2, SENP5, SAE1, UBA2, and UBE2I had differential expressions with different tumor grades." (PMID 34267779, 2021). "From Nanostring nCounter miRNA assay, ubiquitin-like modifier activating enzyme 2 (UBA2) was identified increased in primary and recurrent tumors than normal tissue, revealing the potential connection between UBA2 and tumor recurrence and metastasis." (PMID 34350460, 2021). "Interestingly, UBA2 mRNA expression was significantly induced and strongly correlated with ELAVL1 in the tumor, in contrast to the paired ST of a cohort of patients with HCC." (PMID 38507413, 2024). "However, there still are several limitations, such as the development of brain penetrant inhibitors of UBA2, RALY, FOXD1, and DKK1 that can be selective against tumor cells as well as more studies for clinical research." (PMID 37906341, 2023). "Moreover, SENP1, USPL1, SENP2, SENP5, SAE1, UBA2, and UBE2I had differential expressions with different tumor grades." (PMID 34267779, 2021). "The UBA2 protein expression levels were not related to the age and sex of the patients but were significantly related to the tumor size, Fuhrman grade, and tumor stage." (PMID 34753901, 2021).
tumor (continued). "Because it has been reported that SUMO-1 promotes glycolysis in tumor cells, we investigated whether SAE1/UBA2-mediated SUMOylation is involved in regulating glycolytic metabolism in RA FLSs." (PMID 32938830, 2020). "Moreover, the combined knockdown of UBA2, RALY, and FOXD1 resulted in the smallest tumor volume." (PMID 37906341, 2023). "The biomarkers (RNASeq-derived) LRRC41, UBA2, and WDR77 are more expressed in IDHmut-non-codel compared to IDHwt, suggesting that such molecules can be part of the tumor development through transcriptional enhancing mechanisms." (PMID 41300918, 2025).
cancer (13 papers, 2019 to 2025). A tumor composed of atypical neoplastic, often pleomorphic cells that invade other tissues. "On the other hand, pVEC-ASO3 targets UBA2 mRNA, a cancer hallmark pathology in MYC-driven cancer." (PMID 38391508, 2024). "Our results indicated that higher gene expression levels of RELA were positively correlated with increased IC50 values of cancer therapy drugs, while UBA2, TRIM28, TRIM27, and CAPN3 showed opposite correlations." (PMID 38407971, 2024). "A significantly higher cancer risk was associated with menopause, age, lower BMI, and higher levels of HE4 and UBA2 protein." (PMID 35992817, 2022). "The pVEC-ASO3 targets UBA2 mRNA, a hallmark cancer pathology in MYC-driven cancer, while pVEC-ASO4 has no complementary sequences." (PMID 38391508, 2024). "Reportedly, UBA2 plays a major role in cancer 30-34, but its role in LSCC is yet unclear." (PMID 37056932, 2023). "In a genome-wide study to identify genes which are important for cancer survival through RNAi screening, UBA1 and UBA2 (encoding SAE active subunit) genes have been identified to be essential for survival after knockdown in large pan-cancer RNA interference screens in cancer cell lines." (PMID 33805973, 2021). "The in vitro and in vivo results suggested that UBA2 might play a role in suppressing apoptosis during ccRCC progression, and thus, inhibiting UBA2 expression may be a strategy to prevent the malignant proliferation of cancer cells." (PMID 34753901, 2021). "In addition to being involved in SUMOylation and ubiquitin-mediated proteolysis, UBA2 plays role in regulating cancer cell proliferation, apoptosis, and metastasis in lung and colorectal cancers." (PMID 34753901, 2021). "Strikingly, SS was the most sensitive subtype of cancer to knocking down UBE2I (UBC9), SUMO2 (the most widely expressed SUMO in humans), PIAS1, SAE1 and UBA2 (SAE2), molecules encompassing the entire SUMOylation process and pointing to a selective dependency of SS on this PTM." (PMID 38883782, 2024).
infection (2 papers, 2008 to 2022). The state of being infected such as from the introduction of a foreign agent such as serum, vaccine, antigenic substance or organism. "Knockdown of SUMO-1, SUMO-2/3, and UBC9 significantly elevated the ROS generation by ~2-fold, while UBA2 downregulation elevated ROS levels by ~3-fold compared to MOCK at 30 min post-infection." (PMID 35734580, 2022). "Knockdown of SUMO-1, UBA2, and UBC9 significantly upregulated the production of NO in infected and LPS- and IFNγ-stimulated macrophages by >2-fold at 24 h post-infection." (PMID 35734580, 2022). "Infection of PMA-differentiated THP-1 macrophages with L. donovani promastigotes significantly upregulated the expression levels of SUMO-1, SUMO-2/3, UBA2, and UBC9 by ≥2-fold, while a significant downregulation of SENP1 was observed at 48 h post-infection at the transcript level." (PMID 35734580, 2022). "Knockdown of SUMO-1, UBA2, and UBC9 induced the production of NO upon the infection." (PMID 35734580, 2022). "Interestingly, at 60 min post-infection, a significant elevation of ROS generation was observed upon knockdown of SUMO-2/3 and UBC9 by ~2-fold, SUMO-1 by ~3-fold, AOS-1 by ~4-fold, and UBA2 by ~6-fold compared to MOCK." (PMID 35734580, 2022).
UBA2 also shares sentences with these, for which no sentence is quoted: liver cancer (2 papers); chondrosarcoma (1); colon cancer (1); developmental delay (1); EEC syndrome (1); genodermatosis (1); Hepatic fibrosis (1); inflammation (1); mastitis (1); mental retardation (1); microcephaly (1); rubella (1); small cell lung carcinoma (1); viral infection (1).